HRAS (HRas proto-oncogene, GTPase)
Diseases named in the same sentence as HRAS in open-access papers (continued):
Sharing a sentence is not in itself a finding about the gene and the disease.
cancer (continued). "A significantly greater proportion of HRAS-mutant cancers (48.4%) were found to have co-altered mutations along the RTK/MAPK/PI3K pathways compared to KRAS- (41.4%) and NRAS-mutant (38.4%) cancers (p<0.05 for both)." (PMID 37503077, 2023). "Mutations in the HRAS gene have been reported to be common among different types of cancer; however, the structural and functional effect of the reported mutations remains vague." (PMID 36358305, 2022). "We used in-house published data of the HRAS proto-oncogene for tumor peptides that were investigated as mutations in the genes associated with cancer development." (PMID 36298543, 2022). "Studies have shown that PIK3CA and HRAS are prone to a mutation in a variety of tumors, resulting in their persistent hyperactivity, which promotes cancer cell proliferation and migration." (PMID 35794555, 2022). "It has also been reported that this tumor suppressor gene is found to be deleted and is associated with other genomically colocalized HRAS (Harvey rat sarcoma viral oncogene homolog) pan cancer signature." (PMID 35360070, 2022). "HRAS is also reported as a frequently mutated gene in cancers, subsequently reported as an effective RAS inhibitor." (PMID 36358305, 2022). "We crossed AK2+/− mice with the HRASG12V transgenic (Tg) mouse model of HCC, corresponding to the most frequently mutated form of HRAS found in human cancers." (PMID 35585049, 2022). "The HRAS gene is the most prevalent oncogenes in human cancer; the mutations which lead to the permanent activation of H-Ras are found in 20 to 25% of all human tumors and some fibrotic diseases such as SSc." (PMID 35562771, 2022). "It is also worth noting that there are a number of members of the Ras subfamily of GTPases which are frequently mutated in human cancers, including HRAS, NRAS and most commonly, KRAS, with activating Ras mutations found in ∼20% of cancer patients." (PMID 35119068, 2022). "To achieve that, we focused on a very small target region—one exon of the HRAS gene, commonly mutated in cancer." (PMID 35769342, 2022). "RAS proteins are encoded by the K, N, and HRAS isoforms, each of which undergoes specific cancer-related mutations." (PMID 35546148, 2022). "These somatic mutations are missense and affect residues homologous to the cancer‐associated ones mutated in HRAS, KRAS and NRAS." (PMID 36394128, 2022). "The prognostic value of KRAS and HRAS expression has been evaluated in various types of cancers so far, but only few studies indicated the association between the RAS family overexpression or mutation and the high degree lesions." (PMID 33549031, 2021). "Knocking down PIP5K1A expression specifically reduced the viability of KRAS transformed cells versus NRAS or HRAS mutated cancer cells and had an additive effect with MEK inhibitors in KRAS mutant pancreatic cancer cell models." (PMID 33562401, 2021). "A recent study suggests that TRPML1 expression is significantly elevated in cancer cells bearing oncogenic HRAS mutations, and TRPML1 expression is inversely correlated with patient prognosis." (PMID 33419007, 2021). "Similar to MEK inhibitors (above) and KRASG12C inhibitors (below), tipifarnib treatment of HRAS-mutated cancer cells show adaptive reactivation RTK–WT RAS signaling and enhanced RAF/MEK/ERK pathway activation." (PMID 33924994, 2021). "The potential associations between high HRAS expression levels, age, smoking status and histological type of cancer were observed, which emphasizes the need for further study of the RAS family." (PMID 33549031, 2021). "The farnesyltransferase inhibitor tipifarnib is being tested in patients with HRAS driven cancers and patients with HRAS mutated MTC are eligible (NCT02383927)." (PMID 34489865, 2021). "Two of these hotspots presented cancer stage specificity: HRAS G13 mutations were enriched in TMD in late-stage cancers, while KRAS G12 mutations were depleted in early-stage tumors." (PMID 34307377, 2021).
cancer (continued). "Mutations to the HRAS gene have been associated with several forms of cancer and other diseases such as Costello syndrome." (PMID 35062725, 2021). "In line with this, TRPML1 inhibitor ML-SI1 has successfully suppressed the development of TNBC and cancers bearing HRAS mutations." (PMID 33803964, 2021). "Primary outcome measurement is enrichment of RAS (KRAS, NRAS and HRAS) alterations in BRAF variant cancers." (PMID 33507258, 2021). "RAS proteins play a causal role in human cancer, and the widespread prevalence of RAS mutations (KRAS, NRAS, HRAS) in human cancer has been recognized for many years." (PMID 32100402, 2020). "We selected two transgenic strains of mice: Big Blue, a C56BL/6-derived strain bearing ∼40 integrated copies of lambda phage per cell, and Tg-rasH2, a cancer-predisposed strain carrying four copies of the human HRAS proto-oncogene." (PMID 33318186, 2020). "The three RAS tissue specific isoforms (NRAS, neuroblastoma ras viral oncogene homolog; KRAS, Kirsten rat sarcoma viral oncogene homolog; HRAS, Harvey rat sarcoma viral oncogene homolog) are frequently mutated in cancers." (PMID 32850962, 2020). "Subsequent experiments comparing the proliferation of cancer cells bearing wild-type HRAS and oncogenic HRAS mutations revealed an intrinsic vulnerability of oncogenic HRAS-driven cancer cells to genetic depletion or pharmacological inhibition of TRPML1." (PMID 33322223, 2020). "While the three well-known cancer-associated isoforms K-, N-, and HRAS show >85% amino acid sequence identity indicating functional redundancy, their differential mutation rate in specific tumour types implies cell type-specific roles." (PMID 33138083, 2020). "We investigated HRAS exon 5 mutations in 9397 primary solid tumors of 24 cancer types from the TCGA." (PMID 32012866, 2020). "About one-third of all human cancers exhibit oncogenic mutations in RAS isoforms (KRAS, NRAS, and HRAS) making Ras an important anti-cancer target." (PMID 31856761, 2019). "We recently showed that human cancers with activating mutations in HRAS elevate the expression of MCOLN1, which encodes an endolysosomal cation channel called TRPML1." (PMID 31526156, 2019). "Altogether, the three human Ras genes, KRAS, NRAS, and HRAS, are among the most frequently mutated oncogenes in cancer, cumulatively estimated at 25–30% of all malignancies." (PMID 31712554, 2019). "These mutants were used at the positions Q61 and G12, for NRAS and HRAS respectively, as these are the positions most frequently mutated in human cancer involving NRAS and HRAS mutants." (PMID 29989546, 2018). "KRAS is mutated in nearly a quarter of a wide spectrum of cancers, NRAS is mutated in <10% of cancers, but at a high frequency in specific cancers, while HRAS is rarely mutated in any cancer." (PMID 30194290, 2018). "Among RAS genes, KRAS is the most frequently mutated gene in cancer (85% of RAS-driven cancers), while HRAS is the least frequently mutated gene (3%) (COSMIC)." (PMID 28152508, 2017). "Orthologs of these viral oncogenes were then found in transforming DNA fragments in human cancers in the form of mutated versions of the HRAS and KRAS proto-oncogenes." (PMID 27102293, 2016). "So far it has therefore been believed that the relative frequency of the different HRAS mutations in cancer and CS simply reflects differences in the oncogenic potential of the encoded proteins and differences in the rate they occur by spontaneous mutations." (PMID 27195699, 2016). "Somatic mutations in HRAS are present in many cancers and the vast majority of mutations affect codons 12 and 13 (c.34-39) leading to a constitutively active protein." (PMID 27195699, 2016). "NRAS is also found activated in certain tumor types such as melanoma, whereas HRAS mutations are rarely found in human cancers." (PMID 27330862, 2016).
cancer (continued). "For example, activating mutations in the KRAS gene prevail in lung, colon and pancreatic cancers, while mutations in NRAS and HRAS are rarely found in these cancer types." (PMID 26799184, 2016). "HRAS p.Gly12Val mutations have the highest transforming activity, are very frequent in cancers, but very rare in CS, where they are reported to cause a severe, early lethal, phenotype." (PMID 27195699, 2016). "In both subgroups, there are rare cancer-promoting mutations predicted to activate the PI3K pathway (HRAS, KRAS, PIK3CA, PTEN, and TSC1) and to inactivate the Notch pathway (Notch1 and Notch2)." (PMID 26655088, 2016). "In order to study HRAS mutations we collected HRAS mutant cancer cell lines including KNS-62, NCI-H1915, T24, RL95–2 and KYSE-30." (PMID 26544513, 2015). "Taken together this data shows, that HRAS mutation results in hyperactivation of the RAS pathway in cancer cell lines from various tissues and that this activation sensitizes towards treatment with MEK inhibitors." (PMID 26544513, 2015). "This was further promoted by experiments in which MEK inhibitors do not only cause growth inhibition but also induced apoptosis in HRAS mutant cancer cells." (PMID 26544513, 2015). "The hubs, (Rac1, Cdc42, RhoA, and HRas) identified in the network are widely studied proteins due to their association with human cancers and core cellular processes." (PMID 23028658, 2012). "In accord with the proposed mechanism of action, the decoys eliciting the highest inhibition of cell growth caused in T24 cancer cells a strong decrease of HRAS transcript and activation of caspases 3/7." (PMID 21931711, 2011). "According to the Catalogue of Somatic Mutations in Cancer (COSMIC) database from the Sanger Institute, KRAS mutations occur in only approximately 3% of all cancers of the oral cavity, pharynx, or larynx while HRAS mutations occur in 10% of these cancers." (PMID 19636423, 2009). "In addition, reproductive system was affected mainly in HRAS-mut patients, while malignant tumors were found mostly in patients with HRAS G13R mutation." (PMID 41438146, 2025). "HRAS, a member of the Ras family of GTPases, is frequently mutated in various cancers and the arthritic synovium, leading to the continuous activation of Ras proteins and initiating a cascade of intracellular signals that affect cell growth, differentiation and survival." (PMID 39894825, 2025). "Accordingly, Tipifarnib has found a niche in cancers with HRAS mutations." (PMID 40335986, 2025). "Furthermore, somatic HRAS mutations have also been detected in various malignant tumors, indicating the oncogenic potential of this mutation." (PMID 39839803, 2024). "These predictions might help in planning more experiments to determine how these mutations affect the function of the hRAS protein, which is very important in many types of cancer." (PMID 38420094, 2024). "The three main RAS genes mutated in cancer are HRAS, KRAS, and NRAS." (PMID 38982514, 2024). "Interestingly, the E31K substitution, used to stabilize the complex in the HRasE31K:RALGDS crystal structure, has been reported in cancer samples with HRAS mutations (COSMIC)." (PMID 37833074, 2024). "Oncogenic activity of HRAS caused by point mutations has been observed in cancer patients." (PMID 38338389, 2024). "Comparisons between cancer cells carrying HRAS wildtype and those with oncogenic HRAS mutations have highlighted the vulnerability of oncogenic HRAS-driven cancer cells to genetic and pharmacological TRPML1 inhibition, indicating TRPML1 as a potential target for HRAS-driven cancers." (PMID 38672219, 2024). "The HRAS gene plays a crucial role in regulating essential cellular processes for life, and this gene's misregulation is linked to the development of various types of cancers." (PMID 37153521, 2023). "76% of Ras-mutant cancer patients harbor KRAS mutations versus only 7% with HRAS mutations." (PMID 36864243, 2023).
cancer (continued). "NRAS at 11%, while HRAS accounts for only ~3% of all RAS mutation-dependent cancers." (PMID 37892237, 2023). "HRAS mutations may serve as biomarkers for cancer diagnosis or prognosis or as targets for cancer therapies to inhibit RAS signalling." (PMID 37153521, 2023). "Identifying and characterizing HRAS mutations are vital for cancer diagnosis and treatment." (PMID 37153521, 2023). "Mutations of other isotypes, NRAS and HRAS are found in many human cancers as well." (PMID 37221195, 2023). "The oncogenic Ras isoforms, KRas, HRas and NRas, whose mutations have been found in more than 30% of human cancers, as well as overexpression of growth factors and mutations of their receptors in human cancer, all lead to the activation of this pathway." (PMID 35563547, 2022). "The HRas proto-oncogene GTPase (HRAS) is one of the pathogenic genes that cause cancer." (PMID 36358305, 2022). "For instance, the developmental phenotypes of patients with CS and CS animal models indicate a strong tissue-specific effect of the germline HRAS mutations on the craniofacial development, heart structure and function, skin, and predisposition to specific cancers." (PMID 35230976, 2022). "The HRAS gene has been reported to cause cancer, and identifying alleles that could potentially predispose one to cancer could lead to early diagnosis and better prognosis." (PMID 36358305, 2022). "where mutations in HRAS are associated with a variety of cancers." (PMID 36119517, 2022). "Of particular relevance was the observation that the range of HRAS mutations found in Costello patients had lower potency than those found in sporadic cancers, with worse prognosis and higher tumor predisposition rates in those mutations having stronger RAS activation capacity." (PMID 34062774, 2021). "In fact, the founding members of the RAS gene family in humans (KRAS, NRAS and HRAS) are the most common oncogenes in human cancer, whereas mutations that permanently activate RAS are found in almost 25% of all human tumours and up to 90% in specific types of malignancies." (PMID 34948093, 2021). "Finally, HRAS-driven cancer cells, i.e. cells containing mutations in HRAS, a small GTPase of the Ras superfamily, are vulnerable to TRPML1 inhibition." (PMID 33859333, 2021). "Interestingly, DR5 has been shown to positively regulate cell invasion and metastasis in KRAS-mutated cancer cells while suppressing invasion and metastasis in HRAS mutant animal models, albeit with an undefined underlying mechanism." (PMID 33810241, 2021). "The KRAS, NRAS and HRAS oncogenes are mutated in approximately 30% of all human cancers." (PMID 33924486, 2021). "KRas–the predominantly Ras isoform mutated in cancer–presents a different amino acid in front of the binding pocket (glutamine instead of histidine in position 95) and a more disordered Switch II region even in the active conformation when compared to HRas." (PMID 33681292, 2021). "However, tipifarnib has been evaluated in HRAS mutated cancers only, since KRAS is prenylated by geranylgeranyl transferase and does not need farnesylation for membrane localization." (PMID 33777798, 2021). "However, HRAS mutations that are found in bladder and head and neck squamous cell carcinomas are infrequently seen in other types of cancers." (PMID 34638560, 2021). "Even though mutations in other RAS isoforms, including the neuroblastoma RAS viral (v-ras) oncogene homolog (NRAS) and Harvey rat sarcoma viral oncogene homolog (HRAS) are prevalent in many cancer types, mutations in KRAS account for 85% of all RAS isoform mutations." (PMID 33801965, 2021). "HRAS-mutated cancer cells require RTK–WT RAS signaling to activate RAF/MEK/ERK signaling." (PMID 33924994, 2021).
cancer (continued). "Patients with cancers with mutations in RAS (HRAS, KRAS, and NRAS) had an overall response rate of 31% compared to a response rate of 32% in patients with RET-mutation positive disease with no survival benefit observed in patients with tumors lacking both RET and RAS mutations." (PMID 34489865, 2021). "Mutations in HRAS cause cell overgrowth and are implicated in a variety of cancers." (PMID 32850962, 2020). "More importantly, the findings here may have a general applicability to cancer patients with activating HRAS mutations." (PMID 32460812, 2020). "Future interesting applications of EACCD could include studying molecular markers, such as T1799A point BRAF mutation, TERT mutation, and HRAS mutation as these become available in cancer registries." (PMID 31139148, 2019). "HRAS mutations have been found in various cancer types and represent 1% of all mutations in NSCLC." (PMID 29641535, 2018). "Erastin could be also another potential drug to increase BRAFi therapy, due to the fact that it is an XC− inhibitor and this compound exhibits greater lethality in cancer cells harboring mutations in HRAS, KRAS, or BRAF30,31." (PMID 29487283, 2018). "Human cancer genomics data also provides evidence of the oncogenicity of G12R and G13R substitutions in RAS proteins: KRASG12R accounts for >10% of KRAS-driven PDACs, while HRASG13R is the fourth most frequent HRAS mutation in human cancers and NRASG13R is common in colorectal cancers." (PMID 29233960, 2017). "In addition to cancer, mutations in HRAS and KRAS genes have been associated with the Costello and Noonan syndromes, respectively." (PMID 27713118, 2016). "Finally, we show that blocking access to the fundamental ESE, located in HRAS c.34-39, using a splice switching oligonucleotide (SSOs), causes exon 2 skipping, abolishes production of functional HRAS protein and halts proliferation of cancer cells." (PMID 27195699, 2016). "The effect of the C118S mutation on the ability of wild-type KRAS to promote HRAS oncogenesis may nevertheless be dependent upon the stage of tumorigenesis or types of cancer." (PMID 25902334, 2015). "Our results show that HRAS mutations in cancer activate the RAS and mTOR pathways which might serve as a therapeutic option for patients with HRAS mutant tumors." (PMID 26544513, 2015). "ΔNp63α/v-rasHa-driven carcinomas expressed higher levels of chemokines implicated in recruitment of MDSCs compared to v-rasHa-initiated tumors, providing a heretofore undescribed link between ΔNp63α/HRAS-driven carcinomas and the development of an immunosuppressive TME." (PMID 37638000, 2023). "Moreover, the mutations of HRAS may be associated with the cancer progression and may also increase the risk of tumour recurrence after the anti-cancer treatment." (PMID 33923108, 2021). "In contrast to other HRAS mutations, this polymorphism may only reflect cancer susceptibility." (PMID 25360634, 2014). "However, HRAS mutations are rarely seen in human cancers (4%), and whether romidepsin also inhibits transformation caused by the Ras isoforms most commonly mutated in human cancers (KRAS and NRAS; 21 and 8%, respectively) has not yet been addressed." (PMID 19682393, 2009). "Orthologues of RAS were originally discovered in cancer-causing viruses in rats, leading to the identification of three endogenous human RAS genes, NRAS, KRAS, and HRAS." (PMID 41535418, 2026). "Mutations in RAS oncogenes (KRAS, HRAS, NRAS) are among the most common genetic alterations in human cancers." (PMID 41822354, 2026). "In contrast to KRAS and NRAS, HRAS undergoes exclusively farnesylation through FTase, making FTIs potentially helpful in treating HRAS-mutant cancers." (PMID 40335986, 2025).